KIF14 (kinesin family member 14)
Diseases named in the same sentence as KIF14 in open-access papers (continued):
Sharing a sentence is not in itself a finding about the gene and the disease.
breast tumors (3 papers, 2006 to 2023). "The knockdown of KIF14 inhibits migration and invasion of breast tumor cells in vitro." (PMID 32679794, 2020). "Furthermore, MUC1, a long known cell surface marker overexpressed in a sizeable fraction of breast tumors, and KIF14, a recently proposed candidate at 1q31, presented Discriminating Scores below the threshold and were excluded from our selection." (PMID 17060936, 2006). "KIF14- and Mieap-positive and EZR-negative cells were mainly detected in the torpedo-like structures of the same breast tumors; however, their transcriptomic features differed." (PMID 32679794, 2020). "Distant metastases were more often detected in patients with expression of KIF14 and Mieap at the tips of the torpedo-like structures in breast tumors as compared to KIF14- and Mieap-negative cases (66.7% versus 14.3%, p = 0.003 and 70.0% versus 12.5%, p = 0.001, respectively)." (PMID 32679794, 2020). "It turned out that positive expression of KIF14 and Mieap and negative expression of EZR were mainly observed in torpedo-like structures of the same breast tumors." (PMID 32679794, 2020).
glioblastoma (3 papers, 2020 to 2021). The most malignant astrocytic tumor (WHO grade IV). "Meanwhile, tumor cell growth was inhibited and apoptosis was promoted by silencing KIF14 in glioblastoma." (PMID 34605738, 2021).
lymph node metastasis (3 papers, 2016 to 2021). "The univariate analysis showed that TNM stage (P=0.025), lymph node metastasis (P=0.006) and KIF14 expression (P=0.012) were significantly associated with OS." (PMID 27128470, 2016). "Lymph node metastasis (P=0.003, HR=3.23, 95% confidence interval: 1.58–5.11) and KIF14 expression (P=0.009, HR=1.87, 95% confidence interval: 1.22–3.02) were independent factors as demonstrated by multivariate analysis." (PMID 27128470, 2016). "We also observed that high levels of KIF14 were significantly correlated with TNM stage and lymph node metastasis." (PMID 27128470, 2016). "High levels of KIF14 were significantly correlated with TNM stage (P=0.0044), lymph node metastasis (P=0.0034) and chemoresistance (P<0.0001)." (PMID 27128470, 2016). "In turn, elevated KIF14 levels were more frequently detected in CRC patients with lymph node metastases (p = 0.045) than in those without cancer cells in lymph nodes (36.52% vs. 25.00%)." (PMID 34575892, 2021).
pancreatic adenocarcinoma (3 papers, 2021 to 2025). "Similarly, in pancreatic adenocarcinoma, KIF14 downregulation has been linked to increased tumor invasiveness and poorer survival outcomes." (PMID 40075652, 2025). "High expression of KIF14 is demonstrated to be a significant prognostic biomarker in various cancers, including pancreatic adenocarcinoma (PAAD), hepatocellular carcinoma, cervical cancer and ovarian cancer." (PMID 36227151, 2022). "Through data analysis with the Cancer Genome Atlas (TCGA), we then identified elevated KIF11 and KIF14 mRNA levels of pancreatic adenocarcinomas as independent predictors of reduced survival." (PMID 34208606, 2021). "Functional enrichment analyses were further performed to predict biological functions and pathways related to KIF11 or KIF14, which may possibly impact the course of pancreatic adenocarcinoma." (PMID 34208606, 2021). "We also applied transcriptomics of pancreatic adenocarcinoma patients and healthy donors using publicly available datasets to assess the expression levels and prognostic impact of KIF11 and KIF14 mRNAs." (PMID 34208606, 2021).
bladder cancer (2 papers, 2024 to 2025). "Mechanistically, miR-152-3p directly targets KIF14, leading to a reduction in its expression, which in turn inhibits the PI3K/AKT and FOXM1/CCNB1 pathways, thereby impeding the progression of bladder cancer." (PMID 39606232, 2024). "Studies have shown that KIF14 and KIF23 are aberrantly expressed in bladder cancer." (PMID 40062654, 2025).
cholangiocarcinoma (2 papers, 2025 to 2026). A carcinoma that arises from the intrahepatic biliary tree (intrahepatic cholangiocarcinoma) or from the junction, or adjacent to the junction, of the right and left hepatic ducts (hilar cholangiocarcinoma). "In cholangiocarcinoma, KIF14 binds to the G3BP1/YBX1 complex, leading to the activation of the NF-κB pathway." (PMID 41507134, 2026). "For example, KIF14 was found to promote the proliferation and lymphatic metastasis of cholangiocarcinoma." (PMID 40374610, 2025).
diffuse large B-cell lymphoma (2 papers, 2018 to 2022). "Meanwhile, the expression of KIF14 was markedly associated with MSI in LUAD, UCEC, testicular germ cell tumors (TGCT), STAD, SKCM, SARC, READ, LUSC, GBM, diffuse large B-cell lymphoma (DLBC) in lymphoid neoplasm, COAD and ACC." (PMID 36227151, 2022). "In particular, one genomic study of human diffuse large B-cell lymphoma showed >30% gain of a genomic region containing KIF1439, while recent work indicated that the KIF14 locus was in a genomic region gained in a small cohort of relapsing B-cell precursor acute lymphoblastic leukemia patients." (PMID 30385851, 2018).
lymphoma (2 papers, 2018 to 2021). A malignant (clonal) proliferation of B- lymphocytes or T- lymphocytes which involves the lymph nodes, bone marrow and/or extranodal sites. "It will be interesting to see if KIF14 can accelerate growth of human lymphoma cells, or if its loss can block growth of hematopoietic cancers." (PMID 30385851, 2018). "Our findings of increased fatal lymphomas in mice overexpressing Kif14 suggest that further study of this gene in the context of hematopoietic malignancies is warranted." (PMID 30385851, 2018). "However, Kif14 transgenic mice showed a higher incidence of fatal lymphomas (73 vs. 50%, p = 0.03, Fisher’s exact test), primarily follicular and diffuse B-cell lymphomas." (PMID 30385851, 2018). "In summary, we have shown that although transgenic Kif14 overexpression does not increase mouse mortality or overall tumor burden, it is associated with an increase in fatal lymphomas, plus a lens phenotype in some cases." (PMID 30385851, 2018). "More importantly, in aged transgenic mice and wild-type mice overexpressing KIF14, spontaneous tumor formation of fatal lymphomas was observed, which were mainly follicular and diffuse b-cell lymphomas, providing evidence that KIF14 may be an oncogene in the progression of multiple malignant tumors." (PMID 34495250, 2021). "Overall, this work reveals a novel association of Kif14 overexpression with lymphoma but suggests that Kif14 does not have as prominent a role in initiating cancer in other cell types as it does in accelerating tumour development in response to other oncogenic insults." (PMID 30385851, 2018). "Our results suggest that Kif14 does not act broadly as an initiating oncogene, although may enhance proliferation and severity of cancer, specifically the development of fatal lymphoma, at least in mice." (PMID 30385851, 2018). "KIF14 has not been extensively investigated in blood cancers, although both genomic gain of the KIF14 locus and overexpression have been observed in some human genome-wide lymphoma studies." (PMID 30385851, 2018).
Meckel Gruber syndrome (2 papers, 2024). "Besides, a model of triallelic inheritance of BBS genes was suggested for Bardet-Biedl syndrome, digenic inheritance of unlinked ROM1 and RDS loci was described for retinitis pigmentosa, and digenic trans-heterozygous inheritance of KIF14 and TMEM67 genes—for Meckel Gruber syndrome." (PMID 39180133, 2024).
serous ovarian cancer (2 papers, 2014). "We previously determined that close to 30% of serous ovarian cancers (OvCa tumors) exhibit low-level genomic gain, indicating one mechanism of KIF14 overexpression in tumors." (PMID 24626475, 2014).
adenoma (1 paper, 2025). A neoplasm arising from the epithelium. "Time series analysis using the likelihood ratios showed differences in expression of genes including Fos, Lama3, Aldh1a3, Col7a1 and Doks associated with increased induction by t = 12 h, whereas E2f8, Exo1, Clspn, Kif14 and Kif12 all were decreased in Smad4+/+ adenomas." (PMID 40348815, 2025).
adrenocortical carcinoma (1 paper, 2022). "Both OS and PFS results demonstrated that high KIF14 expression could predict unfavorable prognosis in LUAD, PAAD, mesothelioma (MESO), LIHC, KIRP, KIRC, and adrenocortical carcinoma (ACC)." (PMID 36227151, 2022).
clear cell renal cell carcinoma (1 paper, 2023). "PCR experiments confirmed that higher levels of KIF14 were expressed in clear cell renal cell carcinoma lines such as 769-P and 786-O than in renal normal cells such as HK2." (PMID 37711200, 2023).
colon adenocarcinoma (1 paper, 2021). "Finally, the genes coexpressed with KIF11 or KIF14 in colon adenocarcinoma were identified and functionally annotated." (PMID 34575892, 2021).
endometrial cancer (1 paper, 2025). Primary or metastatic malignant neoplasm involving the endometrium (mucous membrane that lines the endometrial cavity). "In the present study, we identified a significant association between reduced KIF14 expression and the presence of lymphovascular space invasion (LVSI) in endometrial cancer." (PMID 40075652, 2025). "Despite extensive research, its role and function in endometrial cancer remain unclear; to the best of our knowledge, this study is the first to evaluate the clinical significance of KIF14 in EC patients." (PMID 40075652, 2025). "Our findings in endometrial cancer, where high KIF11 expression combined with low KIF14 expression correlates with shorter overall survival, align with these studies." (PMID 40075652, 2025). "This study included the analysis of the expression of proteins KIF11 and KIF14 in endometrial cancer specimens and non-neoplastic endometrial tissues." (PMID 40075652, 2025).
Endometrioid Carcinoma (1 paper, 2025). "Our findings demonstrate a strong and consistent association between KIF11 and KIF14 expression and endometrioid carcinoma (EC), emphasizing their role in tumor progression." (PMID 40075652, 2025). "This study investigates the prognostic significance of KIF11 and KIF14 in endometrioid carcinoma, focusing on their potential as biomarkers and therapeutic targets." (PMID 40075652, 2025). "Our results contribute to the growing body of evidence that KIF14 serves as a prognostic biomarker in endometrioid carcinoma." (PMID 40075652, 2025).
intrauterine growth restriction (1 paper, 2021). "A family with recurrent intrauterine growth restriction and multiple abnormalities was identified as having a new lethal ciliary disorder by trio-WES when autosomal recessive truncating mutations in the KIF14 gene that segregated with the phenotype were detected." (PMID 34234805, 2021).
liver cancer (1 paper, 2021). An epithelial or non-epithelial malignant neoplasm that arises from the liver. "Moreover, liver cancer patients with an increased expression level of KIF14 (p = 0.006), PRIM1 (p = 0.013), and RFC4 (p < 0.001) also had poorer outcomes." (PMID 34681056, 2021).
Meckel Syndrome-12 (1 paper, 2021). "Mutations in the KIF14 gene are described in patients with Meckel Syndrome-12 (OMIM: 616258) and Microcephaly-20 (OMIM: 617914)." (PMID 34946970, 2021).
meningioma (1 paper, 2019). A generally slow growing tumor attached to the dura mater. "Last but not least as for KIF14, despite differential protein and mRNA expression in meningiomas, progression-free survival or proliferation in vitro seemed to be unaffected by KIF14." (PMID 30991738, 2019). "This analysis revealed that high levels of KIFC1 (p = 0.04; HR 1.84), KIF11 (p = 0.03; HR 1.88), KIF14 (p = 0.03; HR 1.91) and KIF20A (p = 0.01; HR 2.13) were associated with a shorter progression-free survival, suggesting kinesins as novel prognostic factors in meningiomas." (PMID 30991738, 2019). "Thus, as compared to the strong effects seen for other kinesin family members, KIF14 may play a minor role in meningioma pathogenesis." (PMID 30991738, 2019). "To finally address the question, if differentially expressed kinesin family members have an impact on tumor cell proliferation of meningioma cells, we performed a siRNA-mediated knockdown of KIFC1, KIF4A, KIF11, KIF14 and KIF20A." (PMID 30991738, 2019). "Therefore, we re-analyzed our previous microarray dataset of benign, atypical, and anaplastic meningiomas (n = 62) and got evidence for differential expression of five kinesins (KIFC1, KIF4A, KIF11, KIF14 and KIF20A)." (PMID 30991738, 2019). "Therefore, we used ten meningioma tissue samples for each WHO grade and stained them for KIFC1, KIF4A, KIF11, KIF14 and KIF20A." (PMID 30991738, 2019). "To query if kinesin family members might represent novel molecular therapeutic targets, we re-analyzed our previous microarray data set of benign, atypical and anaplastic meningiomas and identified five differentially expressed kinesins (KIFC1, KIF4A, KIF11, KIF14 and KIF20A)." (PMID 30991738, 2019).
metastatic colorectal cancer (1 paper, 2021). "In addition, studies have shown that KIF14, a co-expressed gene positively associated with XRCC2, plays an oncogenic role in numerous cancers, FBXW4, a gene negatively associated with XRCC2, acts as a protective factor in metastatic colorectal cancer." (PMID 34051735, 2021).
oral cancer (1 paper, 2024). "Overexpression of KIF14 mRNA has been observed in several types of cancer including oral cancer." (PMID 38016355, 2024).
osteosarcoma (1 paper, 2023). A usually aggressive malignant bone-forming mesenchymal neoplasm, predominantly affecting adolescents and young adults. "Eight out of the 54 hub‐genes (ASPM, CENPF, KIF14, KIF20A, RCC1, SMC2, SRC, and TOP2A) were significantly decreased after NACT (criteria: |fold change| ≥ 2 and adjusted p value < 0.05), consistent with the central role of these hub genes in osteosarcoma." (PMID 37457661, 2023).
pancreatic ductal adenocarcinoma (1 paper, 2021). An infiltrating adenocarcinoma that arises from the epithelial cells of the pancreas. "Based on dichotomized IRS scores, our cohort study revealed that KIF14 protein might be more frequently upregulated (55.88%) than downregulated (44.12%) in pancreatic ductal adenocarcinoma tissues, and that the former expression status independently conferred a better prognosis." (PMID 34208606, 2021).
renal agenesis (1 paper, 2022). Renal agenesis (RA) is a form of renal tract malformation characterized by the complete absence of development of one or both kidneys (unilateral RA or bilateral RA respectively), accompanied by absent ureter(s). "In humans, loss of KIF14, a protein necessary for proper DAP assembly and cilium formation, has been associated with kidney malformations, including renal agenesis and renal dysplasia." (PMID 36222666, 2022).
cancer (61 papers, 2007 to 2026). A tumor composed of atypical neoplastic, often pleomorphic cells that invade other tissues. "Among known membrane-associated cancer mechanisms, KIF14 co-localizes at the cell membrane with AKT and activates AKT by phosphorylation in TNBC, thus starting the signal cascade for the PI3K/AKT pathway." (PMID 39409999, 2024). "Abnormal expression of KIF14 contributed to unfavorable prognosis in patients with cancer, and was associated with cancer cell proliferation and progression." (PMID 36227151, 2022). "KIF14 overexpression is linked to several cancers, and KIF14 causes resistance to sorafenib and chemotherapy through the AKT signaling pathway in cancers." (PMID 35620733, 2022). "Recently, KIF14 was reported to cause tumorigenesis in different cancers, including HCC, and activate AKT." (PMID 33203790, 2020). "This may indicate a concentration-dependent requirement for KIF14 protein in chromosome disjunction, and failure of this association could contribute to cancer progression." (PMID 37091312, 2023). "Studies have found that KIF14 is associated with the occurrence of various cancers." (PMID 35439960, 2022). "Increased expression of KIF14 is associated with a great quantity of human carcinomas." (PMID 35387222, 2022). "Oncogene KIF14 play crucial role in cancer development, but this gene might be associates with progression of pituitary prolactinoma." (PMID 33709028, 2021). "KIF14 has also been found to be associated with poor prognosis in a variety of cancers." (PMID 33408736, 2020). "As the functional roles of KIF14 in human cancer including BC have been documented previously, we chose the poorly characterized KIFC2 as the focus of this study." (PMID 40299549, 2025). "The consistent association across multiple cancer types underscores the potential of KIF11 and KIF14 as prognostic biomarkers and highlights the importance of further investigating their roles in tumor progression and patient outcomes." (PMID 40075652, 2025). "It has been proved that KIF14 is frequently overexpressed in cancers, which correlates with adverse clinical prognoses, tumour metastases and recurrence." (PMID 38498903, 2024). "In the present study, pan-cancer analyses of KIF14 expression were performed via Oncomine and TCGA databases." (PMID 36227151, 2022). "Survival analyses indicated that high expression of KIF14 was correlated with worse prognosis in various cancer types, including LUAD." (PMID 36227151, 2022). "In conclusion, KIF14 was upregulated in various cancers including LUAD, and contributed to unfavorable prognosis in LUAD patients." (PMID 36227151, 2022). "Accumulating evidence indicates that KIF14 participates in the progression of multiple human cancers." (PMID 35156510, 2022). "Increasing evidence have demonstrated KIF14 plays vital roles in regulating tumorigeneses and progression of various cancer." (PMID 36227151, 2022). "In the present study, both expression and survival analyses were conducted on KIF14 in pan-cancer with an emphasis on LUAD." (PMID 36227151, 2022). "We found that KIF11 and KIF14 expression, at both the protein and mRNA level, was markedly altered in cancer tissues compared to respective controls, which was reflected in the clinical outcome of CRC patients." (PMID 34575892, 2021). "KIF14 seems another cancer biomarker that fits well the features of a double-faced protein depending on, e.g., tumor type, cell context, expression levels, and interacting networks, as results across studies are heterogeneous." (PMID 34208606, 2021). "KIF14 is called an oncogenic kinesin, and most reports have shown that it is overexpressed in numerous human cancers and correlated with a poor prognosis." (PMID 34575892, 2021). "As an exciting result, the overexpression of KIF14 significantly reversed the inhibited effect on cancer cells induced by LETM1 silence." (PMID 34605738, 2021).